MSX2 (msh homeobox 2)
Description:
Acts as a transcriptional regulator in bone development. Represses the ALPL promoter activity and antagonizes the stimulatory effect of DLX5 on ALPL expression during osteoblast differentiation. Probable morphogenetic role. May play a role in limb-pattern formation. In osteoblasts, suppresses transcription driven by the osteocalcin FGF response element (OCFRE). Binds to the homeodomain-response element of the ALPL promoter.
Synonyms: HOX8; CRS2; FPP; MSH; PFM; PFM1
Tractability: PROTAC: ubiquitination databases record sites on it.
Gene: Protein-coding gene on chromosome 5 (174,724,582 to 174,730,896, forward strand). Ensembl gene ENSG00000120149.
Subcellular location: Nucleus
Subcellular location (Human Protein Atlas): Nuclear speckles
Pathways (Reactome):
Gene expression (Transcription): Regulation of RUNX2 expression and activity
Gene Ontology:
Molecular function: protein binding; sequence-specific DNA binding; sequence-specific double-stranded DNA binding; DNA-binding transcription factor activity, RNA polymerase II-specific; DNA-binding transcription repressor activity, RNA polymerase II-specific; RNA polymerase II transcription regulatory region sequence-specific DNA binding; transcription cis-regulatory region binding; DNA binding; DNA-binding transcription repressor activity; RNA polymerase II cis-regulatory region sequence-specific DNA binding
Biological process: negative regulation of transcription by RNA polymerase II; cardiac conduction system development; cranial suture morphogenesis; embryonic morphogenesis; negative regulation of DNA-templated transcription; osteoblast differentiation; regulation of transcription by RNA polymerase II; animal organ morphogenesis; regulation of DNA-templated transcription
Cellular component: nuclear speck; chromatin; nucleus; transcription regulator complex
Genetic constraint (gnomAD): Loss-of-function variants: 10 observed, 16.74 expected, observed/expected ratio (o/e) 0.6, 90% interval 0.37 to 1.01. The upper end of that interval is the gene's LOEUF score, 1.01, which puts it in group 4 of 6, group 1 being the genes least tolerant of losing a copy. Missense variants: 339 observed, 348.33 expected, observed/expected ratio (o/e) 0.97, 90% interval 0.89 to 1.07. Synonymous variants: 170 observed, 159.62 expected, observed/expected ratio (o/e) 1.07, 90% interval 0.94 to 1.21.
Gene-disease validity (ClinGen):
ClinGen rates the evidence that MSX2 causes each of these diseases.
craniosynostosis 2 (autosomal dominant): Definitive.
parietal foramina (autosomal dominant): Definitive. Enlarged parietal foramina (EPF) is a developmental defect, characterized by variable intramembranous ossification defects of the parietal bones, which is either asymptomatic, symptomatic (headaches, nausea, vomiting, intellectual disability) or associated with other pathologies.
Homologues: Orthologues: chimpanzee MSX2 (99% identical), pig MSX2 (97% identical), rabbit MSX2 (96% identical), guinea pig MSX2 (95% identical), dog MSX2 (94% identical), macaque MSX2 (93% identical), mouse Msx2 (93% identical), rat Msx2 (93% identical), tropical clawed frog msx2 (71% identical), Drosophila melanogaster Dr (39% identical), Caenorhabditis elegans vab-15 (36% identical). Paralogues in human: MSX1 (58% identical).
Diseases named in the same sentence as MSX2 in open-access papers:
MSX2 is named in the same sentence as 97 diseases in open-access papers, as found by Europe PMC text mining. Sharing a sentence is not in itself a finding about the gene and the disease. The quoted sentences say what the papers report.
breast carcinoma (21 papers, 2010 to 2025). "A comprehensive, large-scale study on breast cancer, however, recently associated the expression of MSX2 with favourable disease characteristics." (PMID 21730974, 2011). "Increased cytoplasmic Msx2 expression was associated with a prolonged breast cancer-specific survival (P = 0.049), recurrence-free survival (P = 0.029) and overall survival (P = 0.019)." (PMID 20682066, 2010). "In agreement with our previous findings, cytoplasmic Msx2 was associated with longer breast cancer-specific survival (BCSS) (P = 0.049), recurrence-free survival (RFS) (P = 0.029), and overall survival (OS) (P = 0.019)." (PMID 20682066, 2010). "Our findings indicate that increased expression of both Msx2 mRNA and protein are associated with improved outcome in breast cancer." (PMID 20682066, 2010). "However, it has become clear from our analysis of two independent patient cohorts that increased Msx2 mRNA and protein expression is associated with improved outcome in breast cancer." (PMID 20682066, 2010). "For example, the function of MSX2 was found to affect the development of several human cancers such as osteosarcoma, breast cancer and pancreatic cancer." (PMID 36192427, 2022). "MSX2 is a regulator of embryonic development, and it is involved in pancreatic and breast cancer, but recently it has been found that it plays a role also in lung adenocarcinoma." (PMID 34262872, 2021). "Here we designate the MLN4924 to be a man with slingshot, who ultimately targets the cicada (SOX2) via oriole (FBXW2) and mantis (MSX2), to regulate stem cell property and sensitize breast cancer cells to tamoxifen." (PMID 31748974, 2020). "FOXC1 interacts with the Bmp-responsive enhancer to reduce Msx2 expression and contribute to skull vault growth in breast cancer." (PMID 26198045, 2016). "XRCC6 interacts with Msx2 (a known TBX3 interactor) and Runx2 (a TBX3 target) and mutations in XRCC6 are associated with breast cancer risk and estrogen exposure." (PMID 24675841, 2014). "MSX2 is likewise a critical regulator of embryonic development that is assumed to play a role in pancreatic and breast cancer." (PMID 23874428, 2013). "Coincidentally, upregulation of p21 in response to MSX2 over-expression was observed both in breast cancer and in our study on malignant melanoma." (PMID 21730974, 2011). "Examination of Msx2 mRNA expression in a breast cancer transcriptomic dataset demonstrated that increased levels of Msx2 were associated with good prognosis (P = 0.011)." (PMID 20682066, 2010). "Msx2 gene expression was first examined in a well-validated breast cancer transcriptomic dataset of 295 patients." (PMID 20682066, 2010). "Previous studies have postulated a role for Msx2 in the advancement of the invasive phenotype in breast cancer." (PMID 20682066, 2010). "This study suggests that increased Msx2 results in improved outcome for breast cancer patients, possibly by increasing the likelihood of tumour cell death by apoptosis." (PMID 20682066, 2010). "The aims of this study were to investigate the potential clinical value of Msx2 as a breast cancer biomarker and to clarify its functional role in vitro." (PMID 20682066, 2010). "The specificity of the Msx2 antibody was validated first by Western blot analysis on a panel of breast cancer cell lines and second by IHC in FFPE breast cancer cell lines." (PMID 20682066, 2010). "A link with the ER signalling pathway is also likely, as previous studies have shown that Msx2 expression can be induced in breast cancer cell lines and breast explants following estradiol or progesterone treatment." (PMID 20682066, 2010). "The aim of this study was to investigate Msx2 expression as a prognostic biomarker in breast cancer." (PMID 20682066, 2010). "Msx2 protein expression was assessed using IHC in a breast cancer TMA constructed from a cohort of 512 patients." (PMID 20682066, 2010).
breast carcinoma (continued). "We conclude that increased Msx2 expression results in improved outcome for breast cancer patients, possibly by increasing the likelihood of tumour cell death by apoptosis." (PMID 20682066, 2010). "Increased levels of MSX2 in breast cancer samples were correlated with a good general prognosis." (PMID 31010135, 2019). "The Foxa2, Msx2, and Zeb2 transcription factors are known to play a role in the epithelial-to-mesenchymal transition and Reln is known to be epigenetically regulated and correlates with prognostic factors in human breast cancer." (PMID 27711132, 2016). "Notably, MSX2 is also abnormally expressed in a variety of carcinoma cells, including adenocarcinoma, breast cancer, and ovarian endometrioid carcinoma, in which MSX2 expression is highly correlated with cell invasion levels." (PMID 27088357, 2016). "The relationship of P, Bmp signaling and Msx2 to breast cancer metastasis remains to be explored." (PMID 22457812, 2012). "Re-activation of the Akp2 gene could be helpful in downregulating aberrant Msx2 expression in PR+ breast cancers." (PMID 22457812, 2012). "However, in a recent study from our group, MSX2 expression was shown to correlate with good prognosis and over-expression of the protein-induced apoptosis in both a breast cancer and a human mammary epithelial cell line." (PMID 21730974, 2011). "The objective of this study was to clarify the role of Msx2 in breast cancer." (PMID 20682066, 2010). "With exception of VANGL2, up-regulation of the genes involved in Wnt signaling pathway, namely WNT5A, MSX2, TCF7L2 and TNFRSF11B, was confirmed in the validation set, further emphasizing the important role of the Wnt signaling pathway in PIK3CA-mutated breast cancer." (PMID 21209903, 2010). "Similarly, ectopic expression of MSX2 in breast cancer cells was shown to elevate p-ERK levels, yet no such correlation could be observed in melanoma." (PMID 21730974, 2011). "However, the results from our clinical study make it clear that Msx2 is a marker of good prognosis in human breast cancer, illustrating the principle that data obtained from in vitro laboratory work must be supplemented by clinical investigation to determine the real prognostic value of a biomarker." (PMID 20682066, 2010). "However, the clinical implications of Msx2 expression in breast cancer are unclear." (PMID 20682066, 2010). "For example, TRIM47, TRIM27, UBR5, and FBXW2 can regulate breast cancer progression and endocrine therapy sensitivities via the polyubiquitination of PKC‐ε, P21, β‐catenin, and MSX2, respectively." (PMID 35843886, 2022). "Biologically, FBXW2 promotes tumor sphere formation by upreglating SOX2 via inducing MSX2 degradation, while MLN4924 sensitizes breast cancer cells to tamoxifen by depleting SOX2 via targeting the FBXW2-MSX2 axis." (PMID 31748974, 2020). "Studies in breast cancer have suggested a link to EMT through induction of Cripto-1 and the c-Src pathway, although this is contradicted by studies showing that Msx2 downregulates the prometastatic factor BSP." (PMID 20682066, 2010). "Our hypothesis that Msx2 is a good prognostic marker in breast cancer was further supported by the subsequent in vitro investigations, when we overexpressed Msx2 in both an immortalized mammary epithelial cell line (MCF10a) and an invasive breast cancer cell line (MDA-MB-231)." (PMID 20682066, 2010). "In ER-/PR-/HER2- breast cancer, ADR could activate CHK1 to regulate cell cycle arrest mediated by MCC-APC/C-cyclinB1 axis and apoptosis induced by MSX2 and BIM." (PMID 32210727, 2020). "The prognostic influence of Msx2 expression has not been investigated in a large cohort of breast cancer patients." (PMID 20682066, 2010). "We also examined the expression of these genes in a separate cohort of 698 luminal (ER/PR+) breast cancers using the TCGA dataset, where PIK3CA-mutant cancers displayed significantly higher expression of eight Wnt genes (LEF1, TCF7L1, TCF7L2, CTNNB1, LRP6, SFRP2, WNT5A, and MSX2)." (PMID 34035258, 2021).
breast carcinoma (continued). "Additionally, immunostaining for Msx2 showed positive cells only in the infiltrating region of human infiltrating breast carcinomas; non-infiltrating tumor cells were negative for Msx2." (PMID 22457812, 2012). "The breast cancer cell lines, SKBR3 and MDA-MB-231, served as positive and negative controls for MSX2 expression, respectively." (PMID 21730974, 2011).
craniosynostosis (20 papers, 2009 to 2025). Craniosynostosis is defined as the premature fusion of one or more cranial sutures leading to secondary distortion of skull shape resulting in skull deformities with a variable presentation. "They described a mutation in the MSX2 gene in a patient with Boston type craniosynostosis." (PMID 33937142, 2021). "FGFRs (FGFR1-3), TWIST, and MSX2 gene mutations are the major causes of syndromic craniosynostosis." (PMID 33731768, 2021). "MSX2 and MSX1 are homeobox genes involved in craniofacial development, that have previously been associated with craniosynostosis." (PMID 36982425, 2023). "Several interesting examples of CNVs resulting in craniosynostosis include IHH regulatory mutations, RUNX2 duplications, and MSX2 duplications." (PMID 29845577, 2018). "It has been therefore postulated that duplications of MSX2 are responsible for craniosynostosis and brachydactyly in Hunter-McAlpine patients." (PMID 23342975, 2013). "The most common and well-characterized cases of craniosynostosis have been caused by mutation in the FGFR1 (fibroblast growth factor receptor 1), FGFR2, FGFR3, TWIST and MSX2 (muscle segment homebox 2) genes." (PMID 20108486, 2009). "Mutations in the genes encoding fibroblast growth factor receptors 1, 2 and 3 (FGFR-1, FGFR-2, FGFR-3), TWIST and MSX2 (muscle segment homebox 2) have been identified in certain syndromic craniosynostosis." (PMID 20108486, 2009). "On the other hand, it would be important to include other genes, such as TCF12 (OMIM 600,480), MSX2 (OMIM 123,101), RAB23 (OMIM 606,144), and EFNB1 (OMIM 300,035), to determine their participation in craniosynostosis in the Mexican population." (PMID 32510873, 2020). "In addition, using SNP analysis, MSX2 does not appear to be the causative agent of craniosynostosis in these rabbits; this was expected as gain-of-function mutations in MSX2 were identified primarily in one family and result in Boston type craniosynostosis in humans." (PMID 23738319, 2013). "Although MSX2 was not identified as a DEG in this analysis, MSX1, whose potential role in craniosynostosis is not well-defined, was increased in lambdoid and sagittal craniosynostosis in the primary model and sagittal craniosynostosis in the male-stratified model." (PMID 36982425, 2023).
pancreatic cancer (7 papers, 2010 to 2025). "Clinical studies showed high MSX2 expression was associated with short survival time in prostate and pancreatic cancer patients." (PMID 28286778, 2017). "The homeobox containing transcription factor MSX2 is a key regulator of embryonic development and has been implicated to have a role in breast and pancreatic cancer." (PMID 21730974, 2011). "MSX2 has been implicated to have a role in breast and pancreatic cancer." (PMID 39654143, 2024). "Consistent with the morphological and molecular changes, MSX2-expressing pancreatic cancer cells showed enhanced cell migration by wound healing scratch assay and two-chamber assay, while down-regulation of MSX2 in Panc-1 is associated with the suppression of cell migration." (PMID 23162473, 2012). "Histopathological studies on pancreatic cancer samples, as well as examination of four infiltrating breast ductal carcinomas, showed an association between MSX2 and more aggressive disease characteristics." (PMID 21730974, 2011). "Indeed, Msx2 has been associated with high tumour grade in pancreatic cancer." (PMID 20682066, 2010). "Study of pancreatic cancer revealed that MSX2 influenced the invasion and migration by inducing the epithelial-mesenchymal transition (EMT) phenotype through upregulation of Twist1 expression." (PMID 28286778, 2017). "The characteristics of MSX2 affecting the migration and invasion of pancreatic cancer cell were also reflected in the appearance of EMT phenotype." (PMID 28286778, 2017). "In this review, we summarize the recently identified roles and functions of MSX2 in the development of pancreatic tumors (PDAC and IPMN)." (PMID 23162473, 2012). "Until recently there has been little information about the expression or function of MSX2 in pancreatic tumors, although both PDAC and IPMN harbor frequent K-ras gene mutations at codon 12 and MSX2 was suggested to be a downstream target of the ras signal." (PMID 23162473, 2012). "In a study of 32 pancreatic cancer patients, high levels of MSX2 significantly correlated with higher tumour grades and vascular invasion." (PMID 21730974, 2011). "In human pancreatic cancer, as well as in a mouse mammary epithelial cell line, ectopic expression of MSX2 was shown to trigger EMT." (PMID 21730974, 2011). "For instance, BMP4- and BMP2- induced MSX2 expression stimulated EMT in pancreatic cancer and cardiac cushion cells, respectively." (PMID 21730974, 2011). "MSX2 enhances the malignant phenotypes of pancreatic cancer, and evaluating MSX2 levels might be useful to differentiate pancreatic cancer from CP." (PMID 25157235, 2014). "Recent studies have clarified the functions of MSX2 in pancreatic tumor development." (PMID 23162473, 2012). "Moreover, over-expression of MSX2 in human pancreatic cancer cells, as well as in mouse mammary epithelial cells, has been shown to induce epithelial-to-mesenchymal transition (EMT)." (PMID 21730974, 2011). "Regarding the functional diversity of MSX2 in breast and pancreatic cancer, DOX-inducible MSX2 over-expression systems were established in both WM793 and 1205Lu cells." (PMID 21730974, 2011). "MSX2 also plays an important role in enhancing the aggressiveness of BD-IPMN, indicating that this gene may be a good therapeutic target in pancreatic tumors." (PMID 23162473, 2012).
Boston type craniosynostosis (6 papers, 2013 to 2023). "An MSX2 gain of function mutation is associated with Boston-type craniosynostosis, which most commonly affects lambdoid and coronal sutures." (PMID 36982425, 2023). "Gain-of-function mutation in msh homeobox 2 (MSX2) causes Boston-type craniosynostosis." (PMID 35451466, 2022). "Moreover, duplications of MSX2 cause Boston type craniosynostosis, whereas intragenic alterations or gene deletions result in parietal foramina, a disorder of deficient ossification of the skull." (PMID 23342975, 2013).